TRAP1 (TNF receptor associated protein 1)
Diseases named in the same sentence as TRAP1 in open-access papers (continued):
Sharing a sentence is not in itself a finding about the gene and the disease.
cancer (continued). "Interest in TRAP1 has considerably grown in recent decades due to its contextual effects in different tumor types: it is highly expressed in several cancers and correlated with drug resistance, but is downregulated in specific tumors with predominant oxidative metabolism." (PMID 36510251, 2022). "Therefore, further studies are required to understand the role of TRAP1 in mitochondrial bioenergetics, apoptotic mechanisms and its expression in specific types of cancer." (PMID 35127545, 2022). "Moreover, multiple studies have confirmed that overexpression of TRAP1 can protect cancer cells from various antitumor drugs." (PMID 36139663, 2022). "Given that TRAP1 is expressed in many cancers, disruption of its regulatory interactions by highly selective inhibitors may help develop innovative anti-neoplastic treatments." (PMID 35614131, 2022). "It is also interesting to point out that TRAP1 expression varies in different types of cancer." (PMID 35127545, 2022). "Our data identify TRAP1 as an F-ATP synthase regulator that can influence cell bioenergetics and survival and can be targeted in pathological conditions where these processes are dysregulated, such as cancer." (PMID 35614131, 2022). "Several lines of evidence suggest increasing correlations between metabolic rearrangements and cancer, with TRAP1 playing an important (but only partially understood) role at a crossroad between glycolytic and OXPHOS metabolic regulation in a tumor-specific way." (PMID 36510251, 2022). "Succinate accumulation may also be due to SDH inhibition by TRAP-1 which is often overexpressed in cancer." (PMID 36344992, 2022). "Combining TRAP1 inhibition with chemotherapy has led to synergistic effects in some cancers." (PMID 34831420, 2021). "Furthermore, TRAP1 inactivation encourages cancer cells to undergo substantial apoptosis, in-vitro and in-vivo; hence, numerous targeting mitochondrial TRAP1 inhibitors have been developed." (PMID 34641473, 2021). "TRAP1 (tumor necrosis factor (TNF) receptor-associated protein 1) is a 90 kDa protein that encodes the mitochondrial chaperone protein Heat Shock Protein (Hsp90) and is closely related to tumorigenesis promotion in a variety of cancers." (PMID 34641473, 2021). "The TRAP1-mediated modulation of mitochondrial functioning in cancer cells may also be conducive to the elevated radioresistance of hypoxic tumors (see Section 3.1)." (PMID 33806538, 2021). "Treatments that inhibit TRAP1 by interacting with an allosteric pocket, such as honokiol bis-dichloroacetate, have been shown to reverse TRAP1 effects in cancer cells, subsequently decreasing proliferation and tumorigenic growth while restoring ROS levels and SDH function." (PMID 34831420, 2021). "TRAP1 is highly expressed in different types of cancer and regulates metabolic rewiring." (PMID 33925645, 2021). "TRAP1 has been extensively investigated in the context of cancer." (PMID 34222342, 2021). "Therefore, the present study focused on developing inhibitors targeting TRAP1 due to its role in cancer—computational studies designed these inhibitors before synthesizing compounds to minimize the time for new drug discovery." (PMID 34641473, 2021). "Tumor necrosis factor receptor associated protein 1 (TRAP1), an anti-apoptotic mitochondrial protein in the heat shock protein 90 (HSP90) family, is involved in mitochondrial metabolism and known to be altered in cancers." (PMID 34831420, 2021). "Thus, aberrant expression of TRAP1 in human malignant tumors is closely correlated with its role in metabolic reprogramming." (PMID 33575209, 2020). "Moreover, several features of TRAP1 biology and its role in cancer cells are consistent with its function in stemness maintenance." (PMID 33065966, 2020). "The identification of TRAP1 as a critical factor regulating the metabolic switch of tumors might provide new insights into cancer therapy." (PMID 33575209, 2020).
cancer (continued). "Accordingly, TRAP1 silencing increases oxygen consumption rate in osteosarcoma cells, while its overexpression in nontransformed fibroblasts reduces mitochondrial respiration and mimics the respiratory pattern of cancer cells." (PMID 31947673, 2020). "Taken together, these findings indicate that TRAP1 inhibitors treatment combined with chemotherapy may become a new therapeutic strategy for cancer." (PMID 33575209, 2020). "This review explores the relationship between aberrant expression of TRAP1 and tumorigenesis, including the molecular mechanisms by which TRAP1 regulates tumor progression; considers the role of TRAP1 in apoptosis; and evaluates the potential therapeutic value of TRAP1 in cancers." (PMID 33575209, 2020). "Thus, although TRAP1 has been proposed to play a key role in the induction of the Warburg phenotype of cancer cells, conflicting studies clearly call for additional research to understand how TRAP1 regulates the mitochondrial metabolism." (PMID 31987035, 2020). "Integrated analysis of public databases and structural predictions indicated that the two affected individuals also had additional variants in genes including TGFB2, TRAP1, PARP1, and EGF, each potentially relevant to cancer risk alone or in conjunction with the SDHA variant." (PMID 30680959, 2019). "So, the selective inhibition of TRAP1 can be interesting for resistant and aggressive cancers." (PMID 35582577, 2019). "In the proband and affected brother, the Thr124Ala variant in PARP1 and the Thr535Ser variant in TRAP1 are of particular interest because like SDHA, these proteins impact mitochondrial function, and defects in PARP1 and TRAP1 have been associated with cancer risk or CAKUT." (PMID 30680959, 2019). "This significant effect confers survival to cancer cells and supports a mainly glycolytic type or Warburg phenotype of metabolism indicating that in certain types of cancers, TRAP1 can also be considered as pro-oncogene depending on the metabolic features of the tumor tissue." (PMID 31540420, 2019). "Proceeding these observations, TRAP1 was found to be dysregulated in several human cancers." (PMID 29621137, 2018). "Alterations of Trap1 expression have been reported in different types of cancer." (PMID 28407697, 2017). "A major question is the mechanism used by cancer cells to modulate TRAP1 expression." (PMID 28177905, 2017). "Hence, in these malignancies, TRAP1 is a candidate biomarker for cancer progression and for prognosis outcome." (PMID 28405578, 2017). "Biologically, TRAP1 modulates the permeability transition pore of mitochondrial inner membrane, and protects the mitochondrial structure from excessive reactive oxygen species (ROS) induced cell death, such as in Parkinson’s disease and cancers." (PMID 28088229, 2017). "Notably, this bioenergetic regulation contributes to retrograde signaling, as SDH inhibition by TRAP1 impacts on the nuclear transcriptional profile of cancer cells through succinate-mediated HIF1α stabilization, thus promoting cancer growth." (PMID 28405578, 2017). "In this review, we analyze how one of these components, the mitochondrial chaperone TRAP1, contributes to the neoplastic process and how TRAP1 targeting might be a new promising therapeutic approach for cancer treatment." (PMID 28405578, 2017). "This suggests that TRAP1 low expressing cancers may be more prone to spread and disseminate from the primary site." (PMID 27977010, 2016). "Although a role of TRAP-1 in tumor progression is recognized, the possibility that ClpXP-directed proteostasis may be also exploited in cancer has been proposed only recently." (PMID 27389535, 2016). "Thus, we suggest that TRAP1 is of crucial importance for cancer cells, particularly under low glucose conditions commonly observed in solid tumors." (PMID 26517089, 2015). "Since Hsp90 family members can protect cancer cells against pro-apoptotic stimuli, we investigated whether TRAP1 also modulates cellular responses to stress stimuli." (PMID 26517089, 2015).
cancer (continued). "Therefore, inhibition of SDH by TRAP1 contributes to the buildup of anti-oxidant defenses in conditions of nutrient depletion that mimic those faced by cancer cells during tumor growth." (PMID 25564869, 2014). "Seven up-regulated genes including CYC1, MIF, LAMB3, TUBB2, UBE2C and TRAP1 had been previously proposed as candidate common cancer biomarkers based on a previous extensive comparison among various cancers and normal tissues which did not, however, include NPC or NP." (PMID 18570662, 2008). "Our identification of C261 and C573 as being both responsible for TRAP1 tetramerization and required for tumorigenic features of an aggressive neoplastic cell model provides the first example of a structure-function relationship linking TRAP1 chaperone activity to cancer cell biology." (PMID 40424720, 2025). "Additionally, TRAP1 plays a role in the metabolic reprogramming of cancer cells." (PMID 41226319, 2025). "Thus, cancer cells may modulate TRAP1 expression to adapt to stress conditions, control the apoptotic threshold and rewire their metabolism from aerobic glycolysis to OXPHOS and vice versa." (PMID 39210159, 2024). "Our study exposes the unknown functions of TRAP-1 in cancer cells." (PMID 37165028, 2023). "In this Opinion paper we have elaborated on, and proposed that NO-dependent regulation of metabolism could go beyond this direct effect and influence key mitochondrial regulators, i.e., TRAP1 and SIRT3, which are involved in cancer-associated increase of antioxidant response and metabolic rewiring." (PMID 35959462, 2022). "Although TRAP1 may have regulatory roles in organellar processes, whether it is ultimately cytoprotective in the context of neurodegenerative diseases or pro-neoplastic in the context of many cancers may reflect two sides of the same coin." (PMID 35883436, 2022). "TRAP1 activity could be critical during Zebrafish development in handling oxidative stress linked to the high rate of proliferation coupled to poorly efficient OXPHOS, in accord with the previously reported antioxidant activity of TRAP1 in cancer cell models." (PMID 33934112, 2021). "Notably, also cancer cells express TRAP1, which enhances cell proliferation." (PMID 34222342, 2021). "Furthermore, TRAP1 mRNA and protein are highly expressed in cancer cell lines and tumors." (PMID 34641473, 2021). "TRAP1 and Sorcin are co-upregulated in cancer, and this feature is considered a marker of drug resistance, but their reciprocal regulation also relates to TRAP1 translational control of Sorcin; indeed, TRAP1 silencing relates to Sorcin protein instability and degradation." (PMID 33946271, 2021). "Finally, this review, besides summarizing how metabolism, oxidative stress adaptation, and chemoresistance are strictly interconnected, also shows how TRAP1 stays at the crossroads of these processes, thus shedding new light on the molecular networks which form the bases of several cancers." (PMID 31947673, 2020). "HSP90 and its mitochondrial paralog, TRAP1, regulate the activity of crucial metabolic circuitries, making cells capable of efficiently using available energy sources, with relevant implications both in healthy conditions and in a variety of disease states and especially cancer." (PMID 32766157, 2020). "Thus, it is intriguing to hypothesize a role for TRAP1 network in the regulation of DNA remodeling because of its ability to reprogram cancer cell fate and metabolism." (PMID 33065966, 2020). "Moreover, only a more detailed examination of how TRAP1 and cellular metabolism affect each other will provide sufficient biological insights to evaluate TRAP1 as a potential drug target for the treatment of cancer and other diseases with a metabolic imbalance." (PMID 31987035, 2020). "Thus, TRAP1 is a very important therapeutic target, and treatment with TRAP1 inhibitors combined with chemotherapeutic agents may become a new therapeutic strategy for cancer." (PMID 33575209, 2020).
cancer (continued). "This cancer stemness-promoting mechanism was based on TRAP1-mediated modulation of the expression of frizzled receptor ligands and β-catenin modification (ubiquitination/phosphorylation), so that TRAP1 upregulated the expression of β-catenin as well as several Wnt/β-catenin target genes." (PMID 32268506, 2020). "Based on the role of TRAP1 in promoting a multidrug-resistant phenotype, combined targeting of TRAP1 and treatment with chemotherapeutic drugs may exert synergistic anticancer activity toward a broad range of human malignant tumors." (PMID 33575209, 2020). "Altogether, these studies confirm the hypothesis that cancer cells modulate the TRAP1 expression to remodel the balance between the glycolytic and oxidative metabolism in response to extracellular stimuli, and that this may be relevant for drug resistance and tumor progression." (PMID 31163702, 2019). "Therefore, when the protein levels of TRAP1 are elevated, glycolysis is the main source of energy for cancer cells, and HIF1a stabilization represents a major mechanism that links TRAP1 to tumorigenesis, thus suggesting an oncogenic role for this molecular chaperone." (PMID 31163702, 2019). "Therefore, TRAP1 might have a central role in shaping inward- and outward-moving mitochondrial signals in cancer cells and in setting the metabolic adaptations they need to thrive." (PMID 28405578, 2017). "Future studies will address the question of whether targeting NRF2 impairs the growth of cancer cells and improve patients' prognosis and whether TRAP1 is another possible therapeutic target, as this chaperone might be responsible for the shift from OXPHOS to glycolysis." (PMID 27070090, 2016). "Current studies suggest that TRAP1 ubiquitination-induced subsequent degradation can lead to mitochondrial dysfunction, which in turn induces cellular stress and may trigger cell death, particularly in cancer cells that are highly dependent on mitochondrial function for survival." (PMID 41322190, 2025). "Second, targeting TRAP1 directly affected HIF-1α, which controls several downstream pathways that initiate VM in cancer cells, notably those of Nodal, VEGF-A, EphA2, and TWIST1." (PMID 40869298, 2025). "TRAP1 prevents the ubiquitin-mediated degradation of CDK1 and MAD2, supporting mitotic progression in cancer cells." (PMID 41226319, 2025). "One of the most studied subfamilies in cancer, the HSPC subfamily (also known as HSP90) presented 2 amp-CNV altered members (HSP90AB1, and TRAP1), and just one del-CNV (HSP90B1)." (PMID 38816397, 2024). "An upregulation of TRAP1, DNAJA3, and DNAJC19 genes is observed across different cancers, offering anti-apoptotic signals to maintain and sustain tumor dormancy." (PMID 38994941, 2024). "TRAP1 and CAMSAP3 expression was greater in the para-cancerous group than in the cancer group with different prognoses." (PMID 38880903, 2024). "Although the promotion effects of TRAP1 in Warburg effect and oxidative phosphorylation (i.e. inhibit or activate SDH) in cancers seemed to be opposing, it was just a result of different metabolic plasticity under different tumor environments." (PMID 38098505, 2023). "Inactivation/loss of TRAP1 has been observed in several neurodegenerative diseases while TRAP1 expression is reported to be elevated in multiple cancers and, as with HSP90, evidence of addiction to TRAP1 has been observed." (PMID 35883436, 2022). "Nevertheless, TRAP1 does appear to play a role in the metabolic adaptation that may sustain neoplastic growth in a nutrient- and oxygen-poor environment; this hypothesis has driven research to mechanistically elucidate a role played by TRAP1 that is common to various cancers." (PMID 35883436, 2022). "TRAP1 is transcriptionally activated by HIF1, in a feed-forward loop between HIF1 and TRAP1, which sustains metabolic adaptations in cancer, as well as during embryonic development and oxidative damage associated to ischemic conditions." (PMID 35959462, 2022).
cancer (continued). "In particular STRAP, TRAP1, and PAK2 refer to TGF-β signaling, whose alteration contributes to many diseases, including cancer and fibrosis." (PMID 35051051, 2021). "Recently several papers have reported that TRAP1, the mitochondrial isoform of the heat shock protein (HSP90), inversely correlated with OXPHOS-coupled ATP synthesis in different normal and cancer cell types." (PMID 34107382, 2021). "In addition, TRAP1 knockdown was found to increase ROS levels, promote mitochondrial c-Src activation, and substantially increase cell motility and invasion, suggesting that cancers with low expression of TRAP1 may be more likely to spread and disseminate from the primary site." (PMID 33575209, 2020). "All these molecules inhibit TRAP1 with a high selectivity over HSP90, abolishing TRAP1-dependent down-regulation of SDH activity in cancer cells and their in vitro tumorigenic growth." (PMID 32766157, 2020). "Extracellular HSPs including HSP90 (α, β, Gp96, Trap1), HSP70, and large and small HSPs have been found in exosomes, oncosomes, membrane surfaces, as well as free HSP in cancer and various pathological conditions, also known as alarmins." (PMID 31533245, 2019). "Thus, it is intriguing to speculate that TRAP1 stability is regulated by post-transductional modifications especially under stress conditions and this allows cancer cells to rapidly modify TRAP1 expression and its downstream protein network in response to extracellular stimuli." (PMID 31878280, 2019). "Similar to TRAP1, the tendency to perform extra-mitochondrial tasks is a common feature of other mitochondrial chaperones, like HSP60 and mortalin, especially in cancer cells." (PMID 30158430, 2018). "TRAP1 is a mainly mitochondrial member of the HSP90 family, whose roles in cancer cell metabolism have been extensively characterized." (PMID 30260431, 2018). "Future studies in cancers and cilia-related congenital disorders are required to elucidate potential clinical relevance of the promising novel biomarker SDOS, and SDOS/TRAP1 cooperation, in these pathological conditions." (PMID 30260431, 2018). "Nodules of TRAP1-overexpressing cells were less than that of control MDA-MB-231 cells, suggesting that TRAP1 overexpression inhibits cancer cell metastasis in vivo." (PMID 26517089, 2015). "Therefore, inactivating SDH mutations in specific cancer subsets, or down-regulation of SDH activity by TRAP1 in a wider number of tumor types, might contribute to the neoplastic process not only by stabilizing HIF1, but also by changing the redox equilibrium of malignant cells." (PMID 25564869, 2014). "This evidence strongly argues for the importance of TRAP1 chaperone activity in the metabolic rewiring and progression of this aggressive cancer type, for which no treatment currently exists." (PMID 40424720, 2025). "Although the biochemical functions of TRAP1 are under intense study for the physiology and treatment of various cancers, its roles in vertebrate development have not been reported." (PMID 40098710, 2025). "Mitochondrial HSP90 homolog TRAP1, but not cytosolic HSP90, binds and stabilizes succinate dehydrogenase-B (SDHB) contributing to HIF-1α-mediated cancer progression in patients carrying SDHB mutations." (PMID 39148727, 2024). "Furthermore, a study that characterized HSP based on the thematic hallmarks of cancers found a surge in the TRAP1 (HSP75), DNAJA3 (TID1), and DNAJC19 (HSP40 C19 member) (HSP40 family proteins) genes across different cancers, proffering anti-apoptotic signals." (PMID 38994941, 2024). "Consequently, besides dampening OXPHOS rate, TRAP1-mediated inhibition of SDH activity results in succinate accumulation, an effect particularly relevant in cancer models characterized by hyperactivation of Ras/ERK signalling." (PMID 35959462, 2022). "Pt1 showed the dominant proliferation of two clones, one of which had an integration into a cancer gene, TRAP1, but its expression level was not increased." (PMID 34786435, 2021).